PLXNA2 (plexin A2)
Diseases named in the same sentence as PLXNA2 in open-access papers:
PLXNA2 is named in the same sentence as 40 diseases in open-access papers, as found by Europe PMC text mining. Sharing a sentence is not in itself a finding about the gene and the disease. The quoted sentences say what the papers report.
melanoma (4 papers, 2015 to 2026). A malignant, usually aggressive tumor composed of atypical, neoplastic melanocytes. "Plexin A2 downregulation was associated with the promotion of migrative and invasive capacities in B0404 melanoma cells." (PMID 34926249, 2021). "Since plexin A2 is semaphorin co-receptor that is involved in focal adhesion and cell migration regulation, the present study suggested that plexin A2 may be implicated in the dacarbazine-mediated phenotypic shift of melanoma cells." (PMID 34926249, 2021). "We then looked at expression and function in melanoma cells of Plexin-A2 and Plexin-A4, the Sema6A receptors." (PMID 25576923, 2015). "The role of PLXNA2 in the regulation of melanoma cell invasion and migration may be a novel marker for the characterization of melanoma cells based on invasive or proliferative phenotypes." (PMID 34926249, 2021). "An in-silico study identified plexin-A2 as a gene that is never mutated in malignant melanomas and may thus be essential for malignant melanoma development and tumor progression." (PMID 37627074, 2023).
pancreatic cancer (4 papers, 2016 to 2022). "Of note, PLXNA2 signaling, found to be affected by somatic mutations in SB.06 cells, has also been found to be associated with adverse outcome in previous studies in pancreas cancer, as well as with a pro-invasive phenotype in prostate cancer." (PMID 26962861, 2016). "Gene enrichment analysis in terms of Jensen DISEASES revealed that genes with germline variants (PLXNA2, FAT2, and SYNE1) enriched in the Maltese breed are also enriched in several cancers, such as endometrial cancer (p < 0.01), pancreatic cancer (p < 0.05), and breast cancer (p < 0.05)." (PMID 31842489, 2019). "This included elements of the Hedgehog signaling pathway (SHH, GAS1), semaphorin signaling (SEMA3A, PLXNA1, PLXNB2, PLXND1, PLXNA2, FARP1, FARP2) and also axon guidance pathways (ROBO1, SLIT1, SLIT3 and SLITRK2), all notable for their involvement in pancreatic cancer progression and metastasis." (PMID 36429078, 2022).
prostate carcinoma (4 papers, 2016 to 2023). A carcinoma that arises from epithelial cells of the prostate gland. "The expression of sema3C, NRP-1, and plexin-A2 is upregulated by monoamine oxidase A (MAOA) in prostate cancer cells." (PMID 37627074, 2023). "The results of a previous study demonstrated that PLXNA2 played a key role in the regulation of perineural invasion of prostate cancer." (PMID 34926249, 2021).
schizophrenia (4 papers, 2019 to 2021). A major psychotic disorder characterized by abnormalities in the perception or expression of reality. "As seen in the previous section, PlxnA2 deficiency in mice leads to altered hippocampal neurogenesis, as well as schizophrenia-like traits." (PMID 34045951, 2021). "Methylation level at three top-sites was associated with expression levels of genes that have been previously linked to psychiatric or behavioral traits in GWASs: FLOT1 (schizophrenia), TUBB (schizophrenia), and PLXNA2 (general risk tolerance)." (PMID 33420481, 2021). "Genome-wide association studies found a significant association between single nucleotide polymorphisms (SNPs) in PlxnA2 gene and schizophrenia in patients with European, European-American, or Latin-American descent." (PMID 34045951, 2021). "However, a link between PlxnA2 mutation and schizophrenia has been found in both humans and mouse models, pointing to an involvement of PlxnA2 signaling in the etiology of schizophrenia." (PMID 34045951, 2021). "This suggests that, in different populations, PlxnA2 may confer varying genetic risk to schizophrenia." (PMID 34045951, 2021). "Interestingly, reduced PLXNA4 expression, another plexin-A family member, have been observed in individual with ASD, while a genetic variant in PLXNA2 has been associated with schizophrenia." (PMID 30736458, 2019). "Interestingly, mice deficient for PlxnA2 show defective hippocampal neurogenesis and impairments in sociability, associative learning and sensorimotor gating, which are traits commonly observed in schizophrenia patients." (PMID 34045951, 2021).
Anxiety (3 papers, 2011 to 2021). Intense feelings of nervousness, tension, or panic often arise in response to interpersonal stresses. "The effect on anxiety in Sema6A mutants is particularly interesting in light of the strong association of PLXNA2 variants with anxiety in humans." (PMID 22132072, 2011). "Although a role of PlxnA2 has been demonstrated in anxiety, from association results it is not possible to determine whether the putative functional role of PlxnA2 takes place during development or in the adult brain (possibly acting on mechanisms regulating neurogenesis)." (PMID 34045951, 2021).
breast carcinoma (3 papers, 2019 to 2023). "However, PLXNA2 has been later reported to be implicated in the proliferation and invasion of breast cancer cells." (PMID 34926249, 2021).
cervical cancer (3 papers, 2014 to 2022). A primary or metastatic malignant neoplasm involving the cervix. "Therefore, KIAA1199 protects cells from Semaphorin 3A- and Plexin A2-dependent cell death in cervical cancer-derived cells." (PMID 25366117, 2014). "As Plexin A2 deficiency enhanced Semaphorin 3A-dependent EGFR phosphorylations and also increased KIAA1199 protein levels, KIAA1199 acts as a pro-survival protein, at least by promoting EGFR signalling to limit Semaphorin 3A- and Plexin A2-mediated cell death in cervical cancer cells." (PMID 25366117, 2014). "One may indeed expect KIAA1199 to directly interfere with pro-apoptotic, Plexin A2-dependent cascades as we demonstrated an additive effect between Semaphorin 3A and EGFR inhibition in triggering apoptosis in cervical cancer cells." (PMID 25366117, 2014).
glioblastoma (3 papers, 2019 to 2023). The most malignant astrocytic tumor (WHO grade IV). "High plexin-A2 expression levels were also linked to worse prognosis in glioblastoma and in prostate cancer (Oncomine, Murat brain dataset,)." (PMID 36658114, 2023). "Similar changes were observed following the silencing of plexin-A2 expression in A172 glioblastoma-derived cells." (PMID 36658114, 2023). "To better understand the involvement of plexin-A2 in glioblastoma we have inhibited the expression of plexin-A2 in U87MG glioblastoma derived cells using several methods, including gene knock-out with CRISPR/Cas9." (PMID 36658114, 2023). "Similar morphological changes and staining for SA-β-gal activity were observed when the expression of plexin-A2 in U87MG cells or in A172 glioblastoma cells was inhibited using shRNAs targeting plexin-A2 expression." (PMID 36658114, 2023). "Our results suggest a novel role for plexin-A2 as a modulator of glioblastoma cells proliferation and indicate that inhibitors of plexin-A2/plexin-A4 may perhaps represent new targets for the development of anti-tumorigenic drugs." (PMID 36658114, 2023). "Plexin-A2 was also found to enable the development of tumors from glioblastoma-derived cells." (PMID 37627074, 2023). "We have silenced the expression of plexin-A2 in U87MG and A172 glioblastoma cells as well as in human umbilical vein-derived endothelial cells (HUVEC) using several specific shRNA species." (PMID 36658114, 2023). "Re-expression of plexin-A2 mutated in its semaphorin binding domain in plexin-A2 knock-out glioblastoma-derived cells did not abrogate rescue of cell proliferation, suggesting that the pro-proliferative effect of plexin-A2 is not activated by the binding of a semaphorin to plexin-A2." (PMID 37627074, 2023).
glioma (3 papers, 2020 to 2021). A benign or malignant brain and spinal cord tumor that arises from glial cells (astrocytes, oligodendrocytes, ependymal cells). "Previous work suggested that semaphorin 3C, plexin A2, plexin D1, and Nrp1 form a complex in glioma stem cells, whereas numerous studies have indicated the interaction of semaphorin 3A, plexins, and Nrp1." (PMID 34270956, 2021). "The quantitative real-time PCR method was used to evaluate mRNA expression of SEMA3(A-G), neuropilins (NRP1 and NRP2), plexins (PLXNA2 and PLXND1), cadherins (CDH1 and CDH2), integrins (ITGB1, ITGB3, ITGA5, and ITGAV), VEGFA and KDR genes in 59 II-IV grade glioma tissues." (PMID 33036421, 2020). "For example, it was reported that the functional complex of SEMA3C with its receptors NRP1/PLXNA2/PLXND1 could activate Rac1/NF-κB signaling to promote the survival and migration of glioma stem-like cells." (PMID 32640719, 2020).
depression (2 papers, 2018 to 2021). "SNPs within the plexin family gene PLXNA2 have previously been implicated in neuroticism, depression, and psychological distress." (PMID 29559929, 2018).
autism (1 paper, 2024). Persistent deficits in social interaction and communication and interaction as well as a markedly restricted repertoire of activity and interest as well as repetitive patterns of behavior. "Thus, PlxnA2−/− mice exhibit symptoms of Schizophrenia, Sema3F−/− mice exhibit symptoms of anxiety and autism, and Sema5A−/− mice exhibit symptoms of autism." (PMID 38646100, 2024).
Cerebral ischemia (1 paper, 2023). Restriction of arterial blood supply to the brain associated with insufficient oxygenation to support the metabolic requirements of the tissue. "Our previous studies found PLXNA2 to be an important mediator of inflammatory responses induced by microglia polarization after cerebral ischemia reperfusion in rats." (PMID 37789455, 2023). "In the current study, it was observed that PLXNA2 may be a direct target gene of miR-212-5p in cerebral ischemia." (PMID 37789455, 2023). "However, little is known about the mechanism of PLXNA2 in cerebral ischemia reperfusion-induced neural injury." (PMID 37789455, 2023).
congenital heart disease (1 paper, 2012). A heart disease that is present at birth. "This is the first study to show a role for this semaphorin receptor in human congenital heart disease, consistent with a Plxna2 mouse knockout phenotype." (PMID 22912587, 2012). "This is the first study to report 1q32.2 deletions at the PLXNA2 locus in patients with congenital heart disease." (PMID 22912587, 2012).
invasive breast ductal carcinoma (1 paper, 2024). "A high expression of PLXNA2 has been associated with invasive breast ductal carcinoma compared to benign tumours, while in ECs, the co-receptor acts as an antiangiogenic and pro-permeability factor through semaphorin 3A signalling." (PMID 38203852, 2024).
ischemic stroke (1 paper, 2023). A stroke disorder caused by obstruction of blood flow to the brain, due to thrombotic (local blood clot formation) or embolic (due to a blood clot or other material traveling from another site) event. "Based on these findings, there is a possibility that PLXNA2 is a downstream target gene for miR-212-5p that may play an important role in impaired functional recovery following ischemic stroke." (PMID 37789455, 2023). "In conclusion, the present study indicated that PLXNA2 may be a target gene of miR-212-5p, and miR-212-5p has great potential as a target for the treatment and diagnosis of ischemic stroke." (PMID 37789455, 2023).
metastatic tumors (1 paper, 2020). "The rest of the PLXNs, i.e., PLXNA2, A4, B1, and B2 were overall either down-regulated or insignificantly differentially expressed in cancer tumors, but all had more decreased expression in metastatic tumors than in primary tumors." (PMID 32640719, 2020). "In addition, PLXNA3, B2, and B3 had further increased, while NRP2 and PLXNA2 had further decreased expression in metastatic tumors than in primary tumors although none of the differences were significant due to the small number of metastatic tumor samples (n = 7)." (PMID 32640719, 2020).
myxoma (1 paper, 2023). A benign soft tissue neoplasm characterized by the presence of spindle and stellate cells, lobulated growth pattern, and myxoid stroma formation. "Moreover, alpha-smooth muscle actin (α-SMA), normally expressed in differentiating cardiomyocytes, was analysed 40% of myxoma cells expressed α SMA, 67% Plexin A2, 55% Semaphorin 3C, and 30% Calretinin." (PMID 37990043, 2023).
Nivelon-Nivelon-Mabille Syndrome (1 paper, 2022). "Of these, four genes were determined to be related to bone development (PLXNA2 with prognathism, HHAT with the complex Nivelon-Nivelon-Mabille Syndrome, MBOAT2 with chondrocyte differentiation, and ITGAV with chondrodystrophy), and one to calcium homeostasis (HPCAL1)." (PMID 36230363, 2022).
osteoporosis (1 paper, 2022). A condition of reduced bone mass, with decreased cortical thickness and a decrease in the number and size of the trabeculae of cancellous bone (but normal chemical composition), resulting in increased fracture incidence. "This study aimed to explore the associations of genetic variants in the semaphorin 3A (SEMA3A) signaling pathway genes, including SEMA3A, NRP1, PLXNA1, PLXNA2 and PLXNA3 with osteoporosis (OP) risk and bone mineral density (BMD) in a Chinese Han older adult population." (PMID 36425469, 2022).
ovarian carcinoma (1 paper, 2020). A malignant neoplasm originating from the surface ovarian epithelium. "At the individual cancer type level, we found that NRP2 and PLXNA2 were positively, while PLXNB1 and C1 were negatively correlated with ovarian cancer stemness score measured with DNAss, but not with RNAss." (PMID 32640719, 2020).
Sensorineural hearing impairment (1 paper, 2019). A type of hearing impairment in one or both ears related to an abnormal functionality of the cochlear nerve. "Hence, whether diminished PLXNA2 expression has a causal effect on sensorineural hearing impairment in FKBP14-kEDS patients requires further investigation." (PMID 31288483, 2019).
cancer (15 papers, 2016 to 2026). A tumor composed of atypical neoplastic, often pleomorphic cells that invade other tissues. "Taken together, PLXNA2, A4, B1, and B2 may mainly associate with tumor suppressor roles in different cancer types and predict better survival." (PMID 32640719, 2020). "Plexin-A2 was previously reported to convey anti-angiogenic signals induced by sema3B and to be downregulated in tumors from several types of cancer." (PMID 36658114, 2023). "The signaling consequences of PLXNA2-semaphorins have been extensively studied in cancers of the nervous system." (PMID 34926249, 2021). "Data from other cancers suggest the involvement of PLXNA2 and PLXNA3 in cell extension and invasion." (PMID 26962861, 2016). "The genes PLXNA1, PLXNA2 and PLXNA4 are enriched in cellular development - axon guidance processes and 68 pan-cancer mutations show a significant clustering of mutations, near a predicted functional site (i.e. based on the most highly conserved positions within the FunFam) and an IBIS PPI site." (PMID 30670742, 2019).
tumor (13 papers, 2014 to 2024). "We pooled all 20 genes (Stx6, Ramp1, Traf3ip1, Nckap5, Pfkfb2, Trmt1l, Rprd1b, Rer1, Sepsecs, Rhobtb1, Tsen15, Abcc3, Arid5b, Tnr, Dock2, Tti1, Fam81a, Oxr1, Plxna2 and Tbc1d31) together as the mouse tumour susceptibility gene signature (mTSGS)." (PMID 39067134, 2024). "Multivariate logistic regression analysis identified SNPs in 2 genes (Plxna2 and Tbc1d31) that were independently associated with tumour metastasis." (PMID 39067134, 2024). "Inhibition of plexin-A2 expression in U87MG cells also results in strong inhibition of their tumor forming ability." (PMID 36658114, 2023). "Plexin-A2 mRNA expression decreased in mouse genetic models of tumor progression, such as the RipTag2 model." (PMID 37627074, 2023). "Among the tumor specimens with IDH mutation, mRNA levels of SEMA3B, SEMA3C, SEMA3D, SEMA3G, NRP2, PLXNA2, and CDH1 were significantly higher (p < 0.05), while SEMA3F, NRP1, ITGB3, ITGA5, and VEGFA genes were under-expressed (p < 0.05)." (PMID 33036421, 2020). "Multivariate analyses flagged SNPs in 20 genes (Stx6, Ramp1, Traf3ip1, Nckap5, Pfkfb2, Trmt1l, Rprd1b, Rer1, Sepsecs, Rhobtb1, Tsen15, Abcc3, Arid5b, Tnr, Dock2, Tti1, Fam81a, Oxr1, Plxna2, and Tbc1d31) independently tied to various tumour characteristics, designated as a mTSGS." (PMID 39067134, 2024). "Lower mRNA expression of SEMA3B, SEMA3D, SEMA3G, and PLXNA2 or higher mRNA expression of SEMA3F, NRP1, ITGB3, ITGA5, and VEGFA genes were detected in the older patient group and associated with the higher tumor grade, wild-type status of IDH, and lower rate of survival time (p < 0.05)." (PMID 33036421, 2020). "Surprisingly though, increased expression of PLXNA2 and PLXNB2 were primarily associated with increased cell resistance to a number of drug treatments, which seems to be contradictory to their primary roles as tumor suppressors." (PMID 32640719, 2020). "We have also previously found that silencing the expression of the plexin-A2/plexin-A4 ligand sema6B in U87MG cells results in the inhibition of proliferation and tumor formation." (PMID 36658114, 2023). "TMPRSS2-ERG fusions are responsible for checkpoint impairment in the cell cycle and for tumor proliferation, but also tumor cell migration and invasiveness by overexpression on metalloproteinase 9 (MMP9) and plexin A2." (PMID 37021836, 2023). "In relation to the malignancy grade of the tumor, mRNA levels of SEMA3B, SEMA3C, SEMA3D, SEMA3G, PLXNA2, and CDH1 decreased while mRNA levels of SEMA3F, NRP1, ITGB3, ITGA5, and VEGFA increased with the increase of the tumor malignancy (p < 0.05)." (PMID 33036421, 2020). "Notably, in one of the experiments we did there was no tumor growth at all from the implanted plexin-A2 silenced cells." (PMID 36658114, 2023).
psychiatric disorder (2 papers, 2021). A disorder characterized by behavioral and/or psychological abnormalities, often accompanied by physical symptoms. "Among the proteins identified as hubs were Plxna2— a semaphorin receptor with a well-established role in axon guidance during CNS development; Plxna2 deficiency has been linked to psychiatric disorders." (PMID 34211495, 2021).
infection (1 paper, 2023). The state of being infected such as from the introduction of a foreign agent such as serum, vaccine, antigenic substance or organism. "The restoration is not due to an artifact caused by infection stress since expression of an empty vector or of the dominant negative form of plexin-A2, which lacks the intracellular domain did not reverse the phosphorylation state to pre-knock-out levels." (PMID 36658114, 2023).
PLXNA2 also shares sentences with these, for which no sentence is quoted: psychological distress (2 papers); astrocytoma (1); benign tumours (1); cardiovascular disease (1); colorectal cancer (1); COVID-19 (1); diabetes mellitus (1); endometrial cancer (1); epilepsy (1); hepatocellular carcinoma (1); Hyperglycemia (1); malaria (1); metastatic cancers (1); osteoarthritis (1); pneumonia (1).